ATG5 (autophagy related 5)
Diseases named in the same sentence as ATG5 in open-access papers (continued):
Sharing a sentence is not in itself a finding about the gene and the disease.
ischemia (5 papers, 2020 to 2024). A hypoperfusion of the BLOOD through an organ or tissue caused by a PATHOLOGIC CONSTRICTION or obstruction of its BLOOD VESSELS, or an absence of BLOOD CIRCULATION. "We isolated infiltrating F4/80+ cells (macrophages) from the kidneys of MΦ atg5−/− mice after 4 days of reperfusion following unilateral renal pedicle clamping-induced ischemia for 31 min." (PMID 38594728, 2024). "Intriguingly, in the young hearts, Atg5 and LC3‐II levels were higher, and lysosome formation (LAMP2) was lower during ischemia and reperfusion than during the sham operation." (PMID 31944526, 2020). "The results also revealed that the expression of miR-30d-5p could significantly inhibit the expression of Beclin-1 and Atg5- by targeting the 3′UTR levels of Beclin-1 and Atg5- and inhibit the ischemia-induced polarization of microglia to M1." (PMID 35585925, 2022). "However, Atg5, LC3‐II, and LAMP2 levels were lower in the aged hearts than in the young hearts during ischemia and reperfusion." (PMID 31944526, 2020).
lymphoma (5 papers, 2015 to 2024). A malignant (clonal) proliferation of B- lymphocytes or T- lymphocytes which involves the lymph nodes, bone marrow and/or extranodal sites.
oral cancer (5 papers, 2015 to 2023). "Inhibition of autophagy by small molecule inhibitors (SMIs) as well as siRNA silencing of ATG5 and Beclin-1 enhanced apoptosis confirming that nimbolide induced autophagy-dependent apoptosis in oral cancer cells." (PMID 30352996, 2018). "To inspect the effect of Beclin 2 depletion and its relationship with autophagy in oral cancer, we transfected siRNAs targeting either beclin 2 or Atg5 in SAS cells." (PMID 26506105, 2015). "Because the Akt/mTOR pathway is known to negatively regulate autophagosome formation, we next examined the correlation of NEDD8 expression with the protein levels of autophagosome components, e.g., Beclin-1, Atg5 and LC3-I/II, in oral cancer cells." (PMID 36890567, 2023). "Moreover, increased expressions of Beclin-1, Atg3, Atg5, Atg7, Atg12, Atg 16, LC3-I, and LC3-II proteins indicated that 4-carbomethoxyl-10-epigyrosanoldie E triggered autophagy in oral cancer cells." (PMID 36275891, 2022).
pancreatic ductal adenocarcinoma (5 papers, 2013 to 2025). An infiltrating adenocarcinoma that arises from the epithelial cells of the pancreas. "While Atg5 and Atg7 are well established core autophagy genes, the role of Unc-51-like kinase 1 (ULK1)—a key autophagy initiator—remains poorly understood in pancreatic ductal adenocarcinoma (PDAC)." (PMID 41408407, 2025).
retinal degeneration (5 papers, 2018 to 2023). Degeneration of the retina. "In addition, complete autophagy deficiency, achieved by deleting Atg5 in neuronal precursors, results in severe retinal degeneration and vision loss at 7 weeks of age while Atg5 deletion in only cones or rods results in much more subtle phenotypes." (PMID 35875981, 2023). "A recent report showed that mice with a deletion of ATG5 or ATG7 specifically in RPE cells developed inflammation in the eye that resulted in an early onset of retinal degeneration." (PMID 30271775, 2018). "It remains to be determined whether increased ATG7 expression may balance out the lower expression of ATG5 systemically or locally, and whether lower ATG5 expression in AIR patients was a specific contributor to or sign of retinal degeneration." (PMID 30271775, 2018).
Stroke (5 papers, 2015 to 2025). Sudden impairment of blood flow to a part of the brain due to occlusion or rupture of an artery to the brain. "Our data suggest that αAsarone alleviates neuronal injury of stroke by facilitating neuronal autophagy through the miR-499-5p/PDCD4/ATG5 signaling pathway." (PMID 39950112, 2025). "Serum ATG5 is dynamically elevated across multiple timepoints after stroke (admission through day 90), with higher levels predicting poor outcomes." (PMID 41007413, 2025). "Peripheral blood was collected from 180 stroke patients for serum ATG5 and T helper (Th) 1, Th2, Th17, and regulatory T (Treg) cell detection via enzyme-linked immunosorbent assays and flow cytometry." (PMID 38511768, 2024). "Serum ATG5 was positively correlated with Th2 and Th17 cells and estimated cognitive function decline in stroke patients." (PMID 38511768, 2024). "This study found that elevated serum ATG5 level was related to elevated Th2 and Th17 cells in stroke patients." (PMID 38511768, 2024). "Regarding the clinical implication of ATG5 in stroke, only one previous study shows that the serum level of ATG5 can be used to identify patients with early-stage ischemic stroke." (PMID 38511768, 2024). "In detail, the median and interquartile range (IQR) of serum ATG5 level were 44.8 (29.2-69.4) ng/mL in stroke patients and 30.5 (19.3-43.1) ng/mL in healthy controls." (PMID 38511768, 2024). "Further, Atg5 and Beclin1 expressions were increased in the WT+stroke+K+TP group when compared with the WT+stroke and WT+stroke+TP groups (^^^P < 0.001)." (PMID 33192177, 2020). "Compared with both the WT and WT+K groups, LC3II/I, Atg5, Beclin1, and p62 expressions were significantly decreased in the WT+stroke and WT+stroke+K groups, respectively (∗∗P < 0.01, ∗∗∗P < 0.001)." (PMID 33192177, 2020). "Single-cell and spatial transcriptomics in human post-stroke tissue remain scarce, but preliminary analyses suggest that increased expression of autophagy-related genes such as ATG5 and PINK1 in microglial-enriched clusters correlates with larger infarct volumes and worse recovery outcomes." (PMID 41007413, 2025). "Serum ATG5 level was elevated in stroke patients compared to healthy controls (P<0.001)." (PMID 38511768, 2024). "In addition, serum ATG5 level was detected at enrollment in stroke patients, while its long-term variation was unclear." (PMID 38511768, 2024). "Finally, the detailed mechanism by which ATG5 regulated Th cell differentiation in stroke requires further investigation." (PMID 38511768, 2024). "Serum ATG5 level had a positive association with Th17 cells (P<0.001) and Th17/Treg ratio (P<0.001) in stroke patients, but not Treg cells (P=0.162)." (PMID 38511768, 2024). "Importantly, serum ATG5 was negatively linked with MMSE score at enrollment (P=0.004), Y1 (P=0.002), Y2 (P=0.014), and Y3 (P=0.001); moreover, it was positively related to 2-year (P=0.024) and 3-year (P=0.012) MMSE score decline in stroke patients." (PMID 38511768, 2024). "However, few studies have indicated the effect of ATG5 on CD4+ T-cell differentiation in stroke." (PMID 38511768, 2024). "Serum ATG5 level was positively correlated to Th2 cells (P=0.022) in stroke patients but not Th1 cells (P=0.164) or Th1/Th2 ratio (P=0.640)." (PMID 38511768, 2024). "Thirdly, this study did not explore other CD4+ T-cell subsets in stroke patients as well as their correlation with ATG5, such as Th9 and Th22 cells." (PMID 38511768, 2024). "Serum ATG5 level was negatively correlated to MMSE score at enrollment (P=0.004), year 1 (P=0.002), year 2 (P=0.014), and year 3 (P=0.001) in stroke patients." (PMID 38511768, 2024). "As healthy controls were enrolled for comparing the expression of ATG5 with stroke patients, CD4+ T-cell subsets of healthy controls were not determined." (PMID 38511768, 2024).
Stroke (continued). "Although serum ATG5 was not related to 1-year MMSE score decline (P=0.058), it was positively associated with 2-year (P=0.024) and 3-year (P=0.012) MMSE score decline in stroke patients." (PMID 38511768, 2024). "Serum ATG5 was elevated in stroke patients compared to HCs (P<0.001) and was positively correlated to Th2 cells (P=0.022), Th17 cells (P<0.001), and Th17/Treg ratio (P<0.001) in stroke patients but not correlated with Th1 cells, Th1/Th2 ratio, or Treg cells (all P>0.050)." (PMID 38511768, 2024).
allergic asthma (4 papers, 2022 to 2023). A asthma with a basis in a pathological type I hypersensitivity reaction. "Meanwhile, the ATG5 knockout (ATG5−/−) mice were used to confirm the effects of ATG5 in allergic asthma." (PMID 37919667, 2023). "Inhibition of miR-26a-5p expression in this study resulted in a significant increase in the expression of LC3A and P62, and a significant decrease in the expression of LC3B, Beclin1 and Atg5, in allergic asthma cells." (PMID 36611831, 2022). "In the OVA-induced allergic asthma mouse model, the expressions of ATG5, LC3, and Beclin 1 in the lungs and lavage fluid decreased." (PMID 36330226, 2022).
cataract (4 papers, 2016 to 2023). Partial or complete opacity of the crystalline lens of one or both eyes that decreases visual acuity and eventually results in blindness. "Tissue-specific knockout of autophagy-related genes Atg5 and Pik3c3 in the lens causes cataracts." (PMID 27294265, 2016). "Studies on lens-specific Atg5−/− mice and Pik3c3/Vps34−/− mice have discovered that impaired autophagy in lenses generates cataracts." (PMID 35954230, 2022). "After 21 months, all Atg5flox/flox;MLR10-Cre mice have severe bilateral cataracts, while a cataract was found in <10% of control mice, suggesting that Atg5 delays formation of age-related cataracts." (PMID 36171977, 2022). "The deletion of Atg5 in mice has been associated with age-related cataracts and the deletion of Pik3C3 with congenital cataracts in mice, although neither deletion alone appeared to affect organelle degradation, and neither molecule has been associated with cataracts in humans." (PMID 36766820, 2023).
cerebral palsy (4 papers, 2017 to 2022). A group of disorders affecting the development of movement and posture, often accompanied by disturbances of sensation, perception, cognition, and behavior. "In cerebral palsy, some researchers demonstrated an association of an ATG5 gene variant and low level of ATG5 protein with cerebral palsy and stronger associations with severe clinical manifestations were identified." (PMID 34661876, 2022). "The gene variant and abnormal expression of ATG5 and ATG7 were also existed strong association with cerebral palsy patients." (PMID 34661876, 2022). "Beyond that, lower plasma ATG5 levels were found in child cerebral palsy patients than control participants." (PMID 34661876, 2022).
chronic kidney disease (4 papers, 2022 to 2025). Impairment of the renal function secondary to chronic kidney damage persisting for three or more months. "Loss of ATG5 or ATG7 in renal epithelium can lead to chronic kidney disease in mice." (PMID 38373978, 2024). "Alterations in Atg5 are related to both acute and chronic kidney diseases in experimental models." (PMID 38594728, 2024). "Many evidence suggests that Atg5 in kidney tubules is involved in kidney repair during transition from AKI to chronic kidney disease (CKD), Tubular specific Atg5 knockout (KO) mice exhibit aggravated IRI or cisplatin induced renal injury and cell apoptosis." (PMID 38594728, 2024).
dementia (4 papers, 2019 to 2024). Loss of intellectual abilities interfering with an individual's social and occupational functions. "Plasma levels of ATG5 were significantly elevated in patients with dementia (149.3 ± 7.5 ng/mL) or MCI (152.9 ± 6.9 ng/mL) compared with the control subjects (129.0 ± 4.1 ng/mL) by Mann-Whitney U-test (p = 0.034, p = 0.016, respectively)." (PMID 30894637, 2019). "In fact, MCI individuals, characterized by an intermediate condition between normal cognitive ageing and dementia, displayed similar levels of both ATG5 and Parkin compared with AD and MD." (PMID 31882960, 2019). "To investigate this topic, we studied the serum levels of specific autophagic markers, (ATG5 protein) and the mitophagic marker (Parkin protein), in a sample of both older patients affected by various forms of dementia and controls." (PMID 31882960, 2019). "Plasma levels of ATG5 were significantly elevated in patients with dementia (149.3 ± 7.5 ng/mL) or MCI (152.9 ± 6.9 ng/mL) compared with the control subjects (129.0 ± 4.1 ng/mL) (p = 0.034, p = 0.016, respectively)." (PMID 30894637, 2019). "Plasma ATG12 and ATG5 levels showed significant group difference between control and patients with dementia and MCI by Kruskal-Wallis test (p = 0.019, p = 0.023, respectively)." (PMID 30894637, 2019). "Moreover, the overall clinical dementia rating (CDR) scores were correlated with ATG5 plasma levels (r = 0.124, p = 0.03)." (PMID 30894637, 2019). "Here, we showed that plasma ATG5 levels were increased both in APP Tg mice and human patients with dementia or MCI compared to healthy control subjects." (PMID 30894637, 2019). "Western blot analysis indicated that plasma ATG5 levels were increased in the dementia patients (n = 2) compared with controls without dementia (n = 2)." (PMID 30894637, 2019).
diabetic cardiomyopathy (4 papers, 2020 to 2025). Diabetic cardiomyopathy is a disorder of the heart muscle in people with diabetes. "The expression of tsRNAs (notably tRF-5014a) in diabetic cardiomyopathy induced by high glucose is up-regulated through negative modulation of autophagy-related 5 (ATG5) protein and influences cellular vitality and pro-inflammatory factor release." (PMID 40247912, 2025).
E. coli infection (4 papers, 2020 to 2022). "Collectively, our data indicate that Z. morio hemolymph limits detrimental inflammatory responses partly by regulating the NLRP3 inflammasome pathway through ATG5/ATG16L1-mediated autophagy pathway during E. coli infection." (PMID 36362066, 2022). "For example, RNAi knockdown of autophagy components (e.g., ATG5, ATG7, and ATG12) caused an increased pathogen load and decreased survival upon E. coli infection." (PMID 34940161, 2021). "However, E. coli infection reduced ATG5 and ATG16L1 expression levels, further decreasing activity of autophagy, which mainly manifested as increased P62 expression level and decreased LC3A/B-II expression level." (PMID 36362066, 2022). "After 8 h, E. coli infection reduced LC3II, ATG5, and Beclin1 expression levels and LC3II to LC3I ratio compared with the control, while LGR-1 pretreatment alleviated this reduction." (PMID 34594329, 2021). "In the present study, a PMEC model of E. coli infection was established to test the hypothesis that L. johnsonii L531 attenuates E. coli–induced inflammation and cell damages by restricting NLRP3 inflammasome activity and promoting ATG5/ATG16L1–mediated autophagy in PMECs." (PMID 32823867, 2020).
esophageal squamous cell carcinoma (4 papers, 2017 to 2024). Esophageal squamous cell carcinoma (ESCC) is a type of esophageal carcinoma (EC) that can affect any part of the esophagus, but is usually located in the upper or middle third. "Our previous study identified CDKL3 as an important oncogene in esophageal squamous cell carcinoma (ESCC) and autophagy-related gene ATG5 was a potential target of CDKL3 in KYSE-150 cell line." (PMID 38562942, 2024).
lung fibrosis (4 papers, 2017 to 2022). "Using the same mice model, Jessop and colleagues demonstrated a greater silica-induced lung fibrosis, together with enhanced inflammation in Atg5+/− mice as compared to their WT littermates." (PMID 33526046, 2021). "Furthermore, bleomycin-induced pulmonary fibrosis in a mouse model led to increased autophagy activation in the lungs as revealed by upregulated ATG5 protein expression levels and increased autophagosome formation." (PMID 28424691, 2017). "In order to decipher the specific role of macrophagic autophagy in the development of lung fibrosis, mice lacking Atg5 gene in their myeloid lineage (Atg5flox/flox LysMCre or Atg5+/−) were exposed to CeO2 NP." (PMID 33526046, 2021).
myocardial ischemia (4 papers, 2017 to 2025). A disorder of cardiac function caused by insufficient blood flow to the muscle tissue of the heart. "We used Western blotting detection to demonstrate that CQ10 noticeably increased the levels of the positively associated autophagy proteins beclin-1 and Atg5 at the same time points of acute myocardial ischemia-reperfusion injury (p < 0.05, n = 6)." (PMID 29348792, 2017). "For example, Tat-Beclin1–stimulated models showed increased Beclin1, LC3-II, and p62, mimicking our 1–2-week-old “enhanced initiation with p62 accumulation “, whereas salvianin B in myocardial ischemia upregulated LC3/Atg5/Beclin1 and reduced p62, consistent with our 2–8-week-old normal autophagy." (PMID 41283520, 2025). "Therefore, the current cardiac oxidative stress, inflammation, and tissue damage in association with upregulation of Atg-5, observed in Old-ISO group, might be explained by the acute stimulation of autophagy during acute cardiac ischemia." (PMID 35416562, 2022).
oral squamous cell carcinoma (4 papers, 2017 to 2025). "In oral squamous cell carcinoma (OSCC), CD46 shows markedly high expression with diffuse strong positivity on tumor cell membranes/cytoplasm, TREM1 is overexpressed, and LC3B/ATG5 expression is low." (PMID 41415031, 2025).
sarcoma (4 papers, 2016 to 2021). A usually aggressive malignant neoplasm of the soft tissue or bone. "In our sarcoma studies we also discovered that Rubicon knock down was significantly more protective against neratinib, [pazopanib + entinostat] and [pazopanib + entinostat + neratinib] when compared to Beclin1/ATG5." (PMID 31380285, 2019). "3-methyladenine or siRNA knockdown of Atg5 was used to evaluate its effect on sarcoma growth." (PMID 27043621, 2016). "In our study, autophagy occurred in cultured sarcoma cells and was downregulated by MAA, 3-methyladenine, and Atg5 siRNA." (PMID 27043621, 2016). "Since the overexpression of the autophagic genes ATG5 and ATG7 in sarcoma 180 cells was induced, we performed monodansylcadaverine staining to verify whether the formation of autophagic vacuoles was induced by the treatment with complex 1 at 1 μM, 4 μM and 20 μM." (PMID 34961767, 2021).